TNF (tumor necrosis factor)
Diseases named in the same sentence as TNF in open-access papers (continued):
Sharing a sentence is not in itself a finding about the gene and the disease.
Sepsis (continued). "The levels of diaphragmatic TNF-α, IL-1β, and IL-6 were increased significantly in rats in the sepsis group compared to rats in the sham group 24 h after surgery (P < 0.01), while TNF-α, IL-1β, and IL-6 concentrations at 24 h after CLP were reduced after NRG-1β treatment (P < 0.01)." (PMID 32765805, 2020). "TNF-α production is mediated via the TLR/NF-κB pathway in activated macrophages during sepsis." (PMID 33003495, 2020). "However, TREM and TNF-α levels in the kidney tissue were significantly lower in the sepsis + cefazolin + etanercept group than those in the sepsis group (p < 0.05)." (PMID 32348434, 2020). "It has been suggested that leptin could act as an acute-phase inflammatory protein, so its circulating concentrations are increased during sepsis and fever and its production can be stimulated by other inflammatory mediators such as TNFα and IL-1." (PMID 33081064, 2020). "It was demonstrated that suppression of TNF-α signaling by anti-TNF-α antibody could result in sepsis resistance." (PMID 32573678, 2020). "We found that THRIL was upregulated in sepsis and may upregulate TNF-α by sponging miR-19a to promote cell apoptosis induced by LPS." (PMID 32944003, 2020). "Delivery of NaHS to sepsis-induced mice leads to a marked increase in lung pro-inflammatory cytokines TNF-α, IL-1β, IL-6, chemokines MIP-1α and MIP-2, and adhesion molecules P-selectin, E-selectin, VCAM-1, and ICAM-1 which affect inflammation and immune cell migration." (PMID 33330130, 2020). "During sepsis, the “cytokine storm” mediates the initial pro-inflammatory phase by releasing proinflammatory cytokines, such as IL-1α, IL-1β, tumor necrosis factor-α (TNF-α), IL-6, and interferon gamma (IFN-γ), among others." (PMID 32630422, 2020). "This study mainly investigated the interactions among THRIL, miR-19a and TNF-α in sepsis." (PMID 32944003, 2020). "In Muc2−/− littermates following LPS challenge, mortality was associated with high circulatory signature sepsis pro-inflammatory cytokines TNF-α, IFN-γ, and IL-1β as early as 3 h that failed to resolve after 24 h." (PMID 31980623, 2020). "However, anti-TNF-α or anti-IL-1 strategies came in vain to prevent death in animal sepsis models, including LPS injection, bacterial injection, and cecal ligation and puncture (CLP)." (PMID 33603756, 2020). "During sepsis, statins affect the production of IL-6, IL-8, TNF, MCP-1, and C-reactive protein." (PMID 33110395, 2020). "Likewise, adjunctive PTX to GENT when administered simultaneous with sepsis initiation significantly decreased the TNF-to-IL-10 concentration ratio in the lung compared to saline controls." (PMID 33072121, 2020). "Activated monocytes and macrophages release large amounts of TNF-α, the main mediator of sepsis." (PMID 32230846, 2020). "Moreover, Cx43 expression was also decreased in the presence of TNF, suggesting that circulating, cardiodepressive cytokines are able to modulate Cx43 expression during sepsis in rodents as well as in septic patients." (PMID 32410859, 2020). "Twenty-four hours after CLP, there were a significant increase in proinflammatory cytokines (TNF-α, IL-1β, and IL-6) in serum and an elevated death rate in rats, while the surviving rats developed septic syndrome; this demonstrated that our sepsis model was successfully established." (PMID 32765805, 2020). "Although first discovered to play a role in the pathogenesis of sepsis, therapies to directly block TNF-α and IL-1β signaling have done more to change the progression and day-to-day symptomatology for patients with a variety of autoimmune and dermatological conditions." (PMID 32849612, 2020). "The reduction of the Cx43 protein might be induced by enhanced circulating TNF concentrations, which arise during sepsis, reducing the electrical and chemical coupling of cardiomyocytes." (PMID 32410859, 2020).
Sepsis (continued). "Notably, although the Csnk1g2 knockout mice looked normal, they died within 18 hr after TNF-α administration, much quicker than their wild-type littermates, indicating that TNF-α-induced systematic sepsis was dramatically enhanced." (PMID 33206046, 2020). "The main difference between IL-6 response in sepsis and training is that in sepsis, there is a marked increase in circulating levels of tumor necrosis factor alpha (TNF-α) and IL-1β, prior to the increase in IL-6, which does not happen after acute or chronic physical exercise." (PMID 32765291, 2020). "Clinical data have revealed that these TNF-α targeting agents may exert certain beneficial effects against sepsis (e.g., improving survival in patients with clinical sepsis)." (PMID 33003495, 2020). "In conclusion, THRIL is upregulated in sepsis and may sponge miR-19a to upregulate TNF-α, thereby promoting cell apoptosis induced by LPS." (PMID 32944003, 2020). "MAPK signaling is suppressed by blocking the phosphorylation of JNK and p38, which decreases the levels of the pro-inflammatory cytokines IL-6 and TNF-α and increases the level of the anti-inflammatory cytokine IL-10 to subsequently alleviate the inflammation in subjects with sepsis-induced ARDS." (PMID 32319516, 2020). "Likewise, in the SGC-CBP30 treated sepsis model, the second wave of serum TNF-α level was dramatically reduced." (PMID 33603756, 2020). "Tumor necrosis factor (TNF) is a well-known mediator of sepsis." (PMID 32410851, 2020). "The levels of serum TNF-α, IL-1β, and IL-6 were increased significantly in rats in the sepsis group compared to rats in the sham group 24 h after surgery (P < 0.01), while TNF-α, IL-1β, and IL-6 concentrations at 24 h after CLP were reduced after NRG-1β treatment (P < 0.01)." (PMID 32765805, 2020). "Genotyping of TNF-α SNPs (-308G/A, -238G/A, -376G/A and +489G/A) was performed for all patients and controls and plasma cytokine levels were measured during the first 24 h after sepsis onset." (PMID 32171247, 2020). "Moreover, compared to the control groups, sepsis group exhibited significantly lower expression levels of miR-19a (p < 0.05) and significantly higher expression levels of TNF-α (p < 0.05)." (PMID 32944003, 2020). "Interestingly, C0127s not only mimicked the effect of XBJ on sepsis progression and cardiac protection, they also regulated the expression of the same genes in TNF-α signaling in the cardiac tissue." (PMID 33986658, 2020). "It is known that an increased level of TNFα in the blood induces sepsis and in the brain, it causes apoptosis of developing oligodendrocytes, mediated by the apoptosis-inducing factor (AIF), which is translocated into the nucleus under the influence of TNFα." (PMID 33374337, 2020). "It has been demonstrated that the most important mediators for orchestrating this imbalance during sepsis are cytokines, such as interleukin-1 (IL-1), IL-6, and tumor necrosis factor-α (TNF-α), but also denatured DNA and cationic proteins, such as histones, released from damaged cells." (PMID 32973526, 2020). "In conclusion, we demonstrate that the pretreatment with etanercept, a TNF-α inhibitor, may ameliorate sepsis-induced oxidative stress, inflammation, and kidney damage." (PMID 32348434, 2020). "In our sepsis model, the injurious pulmonary inflammatory response is closely related to high levels of inflammatory mediators (TNF-α, IL-1β, and IL-6) found in the septic mesenteric lymph, especially with respect to the effect of the amplified inflammatory cascade response seen in septic syndrome." (PMID 33145344, 2020). "More than 20-year-old studies have suggested that TNF may be directly responsible for organ injury during sepsis." (PMID 32410851, 2020). "Noticeably, IL-6 and TNF-α are the primary mediators of local inflammation and sepsis." (PMID 32414062, 2020). "Similarly, we found an increased TNF-α, IL-1β, and IL-6 levels in the serum, the hippocampus, and the frontal cortex at day 1 and day 10 after sepsis onset." (PMID 32457609, 2020).
Sepsis (continued). "Etanercept, a TNF-α inhibitor, may ameliorate sepsis-induced oxidative stress, inflammation, and histopathological damage." (PMID 32348434, 2020). "Depletion of M2 macrophage could induce the secretion of TNF-α during sepsis-induced AKI, and significantly suppress the proliferation of tubular cells, suggesting TNF-α is associated with the tubular cell necrosis." (PMID 32573678, 2020). "In sepsis, the vascular endothelium is activated by lipopolysaccharides (LPS) and/or inflammatory mediators including interleukin-6 (IL-6), tumor necrosis factor-α (TNF-α), and interleukin-1 (IL-1)." (PMID 32964021, 2020). "Indeed, IECs are known to produce both TNF-α and IL-17A, which are critical players in the pathogenesis of sepsis although other sources of TNF-α (macrophages, fibroblasts) and IL-17A (γδ T cells, ILC3) exist especially in the inflamed gut mucosa." (PMID 33182773, 2020). "SST could relieve the injury, the decrease of SSTRs, and the increase of TNF-α and IL-6 induced by sepsis and also further enhanced the expression of IL-10." (PMID 33376482, 2020). "Further evidence has suggested that overexpressed IL-6 and TNF-α by systematic immune responses might support a vital role in the development of myocardial malfunction in sepsis." (PMID 32423469, 2020). "After treatment with rSj-Cys, the levels of these biochemical markers of cardiac injury were significantly reduced, which was associated with the reduction of inflammatory cell infiltration in the heart and the proinflammatory cytokines (IL-6 and TNF-α) in sepsis mice." (PMID 32423469, 2020). "In particular, TNF-α plays a major role in the development of sepsis-induced organ dysfunction." (PMID 32348434, 2020). "Therefore, TNFα, IL-1β, and IL-6 are currently considered to be markers of the early phase of sepsis." (PMID 32793229, 2020). "Furthermore, simvastatin and cerivastatin improved survival rate and reduced serum TNF-α and IL-1β in a murine model of sepsis." (PMID 33110395, 2020). "In addition, TQ acted by reducing sepsis-induced increase in the expression of inflammatory signals including that of IL-1-β, IL-6, and TNF-α in the kidney tissue." (PMID 32626733, 2020). "TRPM7 expression and levels of TNF-α, IL-6 and IL-1β are increased in the serum of patients with sepsis diagnosis and those patients with sepsis and a high expression of TRPM7 have a decreased survival rate in comparison to patients with a low expression of TRPM7." (PMID 33291725, 2020). "Production of TNF-α from activated macrophages can be observed in the early phase of sepsis." (PMID 33003495, 2020). "Previous studies have clearly indicated the importance of IL-1β, IL-6, IL-10, and TNF-α in sepsis." (PMID 33324396, 2020). "The elevation of interleukin (IL)-6, IL-1β, IL-12, IL-17 and tumor necrosis factor (TNF)-α, have been observed in patients with sepsis; therefore, these pro-inflammatory mediators are considered to be the prime cytokines in the pathogenesis of systemic inflammation." (PMID 32397304, 2020). "Indeed, the intravenous infusion of riboflavin into the sepsis mice alleviated the plasma level of pro-inflammatory mediators, such as TNFα, IL-1β, IL-6, INFγ, MCP1, and NO5,6." (PMID 33154451, 2020). "Since some Gzms like GzmA and GzmM seem to be inflammatory mediators responsible of the detrimental effects of LPS in sepsis, including TNF-α production, they also could contribute to altered endothelial permeability." (PMID 32655547, 2020). "Finally, we studied differences between low and high TNF-α producers in endothelial and procoagulant responses, considering their eminent role in sepsis pathogenesis." (PMID 32477337, 2020). "Furthermore, it downregulated the transcriptions of proinflammatory cytokine IL-6, TNF-α, and Il-1β and upregulated IL-10 transcription in the liver of sepsis mice." (PMID 32457606, 2020).
Sepsis (continued). "Potentially, variations in TNF-α and IL-6 protein expression in samples from sepsis patients after LPS challenge may be explained by when blood samples were taken in relation to the different phases of sepsis." (PMID 33382782, 2020). "In the early phase of sepsis, TNF-α is synthesized and released into systemic circulation." (PMID 33003495, 2020). "However, male KO mice had significantly higher levels of TNFα and IL-6 after sepsis when compared to male WT septic mice, while levels of IL-10 and KC were similar in both WT and KO male mice." (PMID 32117320, 2020). "An important finding of the present report is the protective role of the TNF-α +489G/A polymorphism against sepsis and septic shock development; however, it did not influence mortality in septic adult Caucasian patients." (PMID 32171247, 2020). "TNF-α has been involved in sepsis immunodepression through increased apoptosis." (PMID 32171247, 2020). "Moreover, the protective effect of PD against the sepsis-induced increase in serum cytokines, including TNF-α, IL-1β, and IL-6, was inhibited by mdivi-1 treatment." (PMID 32131850, 2020). "Both anti-TNF-α and recombinant murine IL-10 injected subcutaneously improved survival of E. coli sepsis in neonatal mice, indicating a role of IL-10 in improved outcome of sepsis in these animals." (PMID 33072121, 2020). "Pathogenesis may involve the release of TNF, endothelin, catecholamines, vasopressin, and angiotensin-II in those with severe sepsis." (PMID 33072437, 2020). "This speculation is based on previous studies, in which the plasma concentration of IL-10 was decreased by the administration of antimonoclonal TNF-α antibodies in chimpanzees with sepsis." (PMID 32766286, 2020). "An in vivo study involving an LPS-stimulated mouse model of sepsis reported reduced levels of inflammatory mediators (TNF-α, IL-1β, and IL-6) and an elevated level of the anti-inflammatory cytokine IL-10 in septic mice fed with lyophilized powder of wild bitter gourd-supplemented diet." (PMID 33193799, 2020). "Additionally, sepsis-induced lymphocyte depletion was ameliorated, levels of circulating pro-inflammatory cytokines TNF-α and IL-6 were increased, anti-inflammatory IL-10 levels were decreased and bacterial clearance was enhanced." (PMID 33336293, 2020). "Furthermore, the contents of TNF-α, IL-6, and IL-10 were detected in order to study the inflammation in mice with sepsis." (PMID 33376482, 2020). "Both pro and anti-inflammatory mediators were elevated in in a murine model of sepsis with early deaths and high Interleukin- 6, Tumor necrosis factor α (TNF-α), Macrophage inflammatory protein 2 (MIP-2), Interleukin 1 receptor antagonist (IL-1ra) predicted mortality within 24 h." (PMID 32175298, 2020). "IL-6, IL-1β and TNF-α are among the major cytokines responsible for sepsis disease pathogenesis." (PMID 32117233, 2020). "Specifically, the BEC glycocalyx and in particular HS proteoglycans are rapidly shed in response to inflammation as induced by cytokines, such as TNF, but also in various experimental and pathological inflammatory conditions, such as ischemia reperfusion injury or sepsis." (PMID 31636638, 2019). "Past statin use may attenuate system inflammations, such as sepsis (TNF-α and IL-6) or acute lung injury, with multiple organ failure as demonstrated in a previous study supporting our result." (PMID 31474854, 2019). "In addition, elevations of IL-6 can be found in a variety of severe insults, such as trauma, burns, hemorrhagic shock, sepsis, and ischemia-reperfusion injuries together with IL-1 and TNF-α." (PMID 31336570, 2019). "In contrast to early onset inflammatory mediators of sepsis (namely, tumor necrosis factor and interleukin-1), which return to baseline early in murine models, HMGB1 levels remain elevated for at least 4 weeks after experimental sepsis induced by cecal ligation and puncture." (PMID 31892321, 2019).
Sepsis (continued). "In the present study, DEX increased TNF-induced PTX3 mRNA stability indicating the involvement of post-transcriptional mechanism as has been shown in mononuclear cells upon LPS stimulation in the context of sepsis." (PMID 31437159, 2019). "TNF-α and IL-1β are prototype pro-inflammatory cytokines involved in the pathogenesis of sepsis." (PMID 31818040, 2019). "Furthermore, we demonstrated the inhibitory effects of LDK378 on the sepsis-induced up-expression of TNF-a and IL-6 and the enhanced effects of LDK378 on IL-10 expression in septic rats." (PMID 30820191, 2019). "In canine studies modeling sepsis through injection of lipopolysaccharide (LPS), treated dogs had greater blood IL-6, IL-10, TNF-α, and KC-like concentrations up to 4-h post-injection and greater CCL2 up to 24-h post-injection, when compared to placebo-treated dogs." (PMID 31316998, 2019). "In fact, cumulative evidence supports the role of the Wnt pathway in the regulation of the macrophage-mediated inflammatory response in sepsis, in which Wnt3a and Wnt6 reduce TNFα secretion and promote the differentiation towards an M2 anti-inflammatory phenotype attenuating the immune response." (PMID 31665078, 2019). "During sepsis, the homeostasis between pro-inflammatory and anti-inflammatory cytokines is disrupted, resulting in the release of inflammatory factors, such as IL-6, IL-1β, and TNF-α." (PMID 31555126, 2019). "Macrophages are one of the major early sources of TNFα, IL-6, and prostaglandins during sepsis." (PMID 31244655, 2019). "Furthermore, APC increases the survival of patients with sepsis through its anti-inflammatory effect by reducing both NF-κB pathway and expression of pro-inflammatory cytokines such as TNF-α and IL-6 induced by LPS." (PMID 31315617, 2019). "Notably, early clenbuterol treatment alleviated sepsis-induced cognitive deficits by polarizing microglia toward an anti-inflammatory phenotype, reducing proinflammatory cytokines including IL-1β, TNF-α, and up-regulating CREB/BDNF, PSD95, and GluN2B." (PMID 31354429, 2019). "However, HDACs activity (e.g., HDAC6 and HDAC11) are off balanced during sepsis, which alters the transcription of pro- and anti-inflammatory genes (e.g., TNF-α and IL-10, respectively) in vitro and in vivo." (PMID 31416265, 2019). "This might be attributed to that lnc‐THRIL might initiate the transcription of TNF‐α and thereby promote the inflammatory response in sepsis patients, which aggravated disease condition in sepsis patients." (PMID 31257645, 2019). "TNF-α is a key inflammatory mediator in LPS-induced toxicity and sepsis." (PMID 31186277, 2019). "However, several studies, in line with our own observations, demonstrated that early TNFα release (i.e., measured close to the onset of sepsis) correlates with mortality." (PMID 31297113, 2019). "Under the combined action of anti-inflammatory cytokines, a sustained increase in TNF-α levels leads to an aggravation of inflammation, and this also involves organ damage, which results in an increase in the mortality rate in patients with sepsis." (PMID 31671729, 2019). "Moreover, in severe sepsis model (cecum ligated for 1cm in CLP procedure), Ets2-deficient mice also showed increased IL-6 and TNF-α production in serum and poor survival." (PMID 31785145, 2019). "However, in the current study, HMGB1 increased quickly during the early phase of sepsis, which is 12 h after the model was established and then dropped rapidly, a similar pattern as TNF-α." (PMID 31420571, 2019). "However, in a mouse sepsis model, pfbA mutant strain-infected mice showed significantly higher mortality and TNF-α levels in blood." (PMID 31482074, 2019). "However, up until now, 18 different clinical trials using TNF inhibitors have been performed in sepsis patients with very minimal impact on the survival rates." (PMID 31787972, 2019). "Cytokines, such as TNF-α and IL-1β, are extensively produced at the early stage of sepsis." (PMID 31671563, 2019).